MALAT1 (metastasis associated lung adenocarcinoma transcript 1)
Diseases named in the same sentence as MALAT1 in open-access papers (continued):
Sharing a sentence is not in itself a finding about the gene and the disease.
osteosarcoma (continued). "For example, MALAT1 increases stem cell-like properties by up-regulating RET in sponge mir-129-5p, thus activating the PI3K-Akt signaling pathway and providing potential therapeutic targets for osteosarcoma treatment." (PMID 32883200, 2020). "Further, we checked the levels of MALAT1 in osteosarcoma patients versus archived samples from individuals with no osteosarcoma diagnosis." (PMID 32728178, 2020). "Comparison of different lncRNAs in tumor samples from osteosarcoma with and without lung metastasis led to identification of MALAT1 as the most differentially upregulated lncRNA in the osteosarcoma patients with lung metastasis." (PMID 32728178, 2020). "And there were 38 endogenous genes (including ARF1, HSP90AB1, and TUBA1B), 53 TFs (including E2F1, NFKB1, and EGR1), and 858 ncRNAs (including MALAT1, miR-590-3p, and TUG1) were considered as key regulators of osteosarcoma through a series of function enrichment analysis and network analysis." (PMID 30936265, 2019). "Moreover, the downregulation of MALAT-1 reduces tumorigenesis in mice implanted with osteosarcoma cell lines HOS and U2OS cells transfected with MALAT-1 siRNA in comparison to mice implanted with HOS and USO2 cells transfected with non-specific siRNA." (PMID 29657304, 2018). "The lncRNA MALAT1 reduces the protein expression levels of RhoA, ROCK1, and ROCK2, indicating that MALAT1 may promote osteosarcoma cell migration by the RhoA/ROCK pathway; then, MALAT1 increases the number of actin stress fibers in osteosarcoma cells." (PMID 29618386, 2018). "Lastly, the incorporation assays as well as CCK-8 assays and transwell assays were re-executed to finally determine whether MALAT1 could regulate ROCK1/ROCK2 and their mediated proliferation/metastasis via a ceRNA of miR-144-3p in osteosarcoma cells MNNG/HOS." (PMID 28938647, 2017). "Our results showed that MALAT1 was up-regulated in primary osteosarcoma tissues compared to noncancerous tissues (P<0.001)." (PMID 29290978, 2017). "Previous study has demonstrated that miR-144 could suppress osteosarcoma growth and metastasis by targeting ROCK1 and ROCK2, so we wondered whether there was a similar “ceRNA” network among MALAT1, ROCK1/ROCK2 and miR-144-3p." (PMID 28938647, 2017). "Recently, Dong found that MALAT1 could activate the PI3K/Akt pathway to promote cell proliferation, invasion and metastasis of osteosarcoma." (PMID 28938647, 2017). "RT-qPCR was used to detect MALAT1 expression in 64 primary osteosarcoma tissues and paired adjacent noncancerous tissues, normalized to GAPDH." (PMID 29290978, 2017). "MALAT1 was significantly upregulated in human osteosarcoma tissue compared with paired non-tumor tissue." (PMID 28353666, 2017). "MALAT1 has been shown to regulate tumor progression and metastasis by modulating different signaling pathways, including the Snail pathway in colon cancer, PI3K/Akt pathway in osteosarcoma cells, and ERK/MAPK pathway in gallbladder cancer cells." (PMID 27600237, 2015). "Although the role of lncRNA-MALAT1 in miR-206/CDK9 axis-mediated osteosarcoma proliferation remains unclear, the findings indicate that the MALAT1/miR-206/CDK9 axis may provide novel insights into the biological mechanisms of osteosarcoma progression." (PMID 36903369, 2023). "While our work supports MALAT1-miR-202 as a signature for lung metastasis of osteosarcoma, we can not comment on whether or not this represents a signature unique to lung metastasis." (PMID 32728178, 2020). "Additionally, the osteosarcoma tissues in 66.2% (43 of 64) of cases had at least 2-fold higher expression of MALAT1 than noncancerous tissues." (PMID 29290978, 2017). "However, the functional roles of MALAT1 in the tumorigenesis and progression of osteosarcoma have not been extensively studied." (PMID 28938647, 2017). "Additionally, a significant negative correlation was also found between MALAT1 and miR-205 expression in 64 primary osteosarcoma tissues." (PMID 29290978, 2017).
bladder cancer (121 papers, 2012 to 2025). "Urinary EVs lncRNA PCAT‐1 and MALAT1 overexpression in bladder cancer were linked to a poor recurrence‐free survival rate and facilitated recurrence prediction." (PMID 39611045, 2024). "A meta-analysis investigating the relationship between lncRNA MALAT1 expression and prognosis in bladder cancer found that elevated levels of lncRNA MALAT1 are associated with a poor prognosis and an increased risk of lymph node metastasis in these patients." (PMID 39628486, 2024). "The expression of MALAT1, an important epigenetic regulator implicated in oncogenic pathways in a range of tumor types, is dysregulated in bladder cancer." (PMID 36902032, 2023). "MiR-125b was downregulated in bladder cancer, and its overexpression decreased the expression of MALAT1, causing an inhibition of bladder cancer cell proliferation, motility, and activation of apoptosis." (PMID 29147648, 2017). "On the other hand, MALAT1 in bladder cancer cells is reported to associate with a polycomb repressive component, SUZ12." (PMID 27250026, 2016). "Mutations in the MALAT1 gene, recently discovered in human cancers, are rare in breast (1.1%) as compared with other cancer types such as bladder cancer (15.3%)." (PMID 27172249, 2016). "In bladder cancer, downregulation of MALAT-1 led to the inhibition of the EMT associated genes ZEB1, ZEB2, and Slug, and the activation of E-cadherin." (PMID 26932376, 2014). "Only 12 studies focused on exosomal multiple-ncRNA assay in bladder cancer detection, while 34 studies investigated single-ncRNA assay, of which 7 studies probed into the diagnostic value of exosomal single UCA1 in bladder cancer and 6 studies explored single MALAT1." (PMID 38227115, 2024). "Both single-exosomal UCA1 and single-exosomal MALAT1 exhibited relatively satisfactory diagnostic accuracy with an AUC of 0.77 and 0.79, respectively, manifesting their potential as noninvasive diagnostic biomarkers for bladder cancer." (PMID 38227115, 2024). "Additionally, a novel biomarker of bladder cancer has been found is exosome, numerous studies investigating the association between exosomes and bladder cancer have identified the presence of exosome MALAT1, PCAT-1, and PTENP17." (PMID 38594513, 2024). "In addition, lncRNA MALAT1 inhibition has been associated with down-regulation of fibronectin in bladder cancer cells." (PMID 31619581, 2019). "Therefore, we carried out a meta-analysis on the association between abnormally expressed MALAT1 and the OS of bladder cancer patients." (PMID 29899709, 2018). "Metastasis-associated lung adenocarcinoma transcript 1 (MALAT1), a long non-coding RNA transcribed from gene locus on chromosome 11q13, is reported to be associated with a variety of human tumors, such as lung, gastric and bladder cancer." (PMID 29416703, 2018). "MALAT1 overexpression was reported to have a significant association with the grade and metastasis in bladder cancer, indicating that MALAT1 may be used as a prognostic biomarker in bladder cancer." (PMID 36685879, 2022). "However, MALAT1, as one of the long noncoding RNAs that epigenetically and post‐transcriptionally regulates gene expression, has been associated with the tumorigenesis of most cancer types, including bladder cancer." (PMID 33634966, 2021). "However, MALAT1 was investigated in two studies, so we carried out a meta-analysis on the association between abnormally expressed MALAT1 and the OS of bladder cancer patients." (PMID 29899709, 2018). "MALAT1 (Metastasis Associated Lung Adenocarcinoma Transcript 1) was originally identified to be highly expressed in metastatic small cell lung cancer, but recent studies showed that MALAT1 is upregulated in bladder cancer and its expression level corresponds to the tumor grade and metastatic stage." (PMID 24006935, 2013). "Up-regulated MALAT-1 contributes to bladder cancer cell migration by inducing epithelial-to-mesenchymal transition." (PMID 41303378, 2025).
bladder cancer (continued). "Beyond LINC01094, other lncRNAs—including MALAT1, UCA1, and XIST, among others—have also been implicated in bladder cancer progression or metabolic reprogramming." (PMID 40438104, 2025). "Urinary exosomes from 42 bladder cancer patients were collected and quantified for seven lncRNAs (UCA1, H19, MALAT1, TUG1, GAS5, RMRP, and LINC01517), showing increased expression of RMRP, UCA1, and MALAT1 in bladder cancer patients." (PMID 40075875, 2025). "The results showed that the expression of MALAT1 long non-coding RNA (LncRNA) was decreased in bladder cancer cells (5637 and T24 cells), and the phenotype of bladder cancer was changed under blue light." (PMID 38524179, 2024). "Upon knocking down MALAT-1, the expression of the epithelial-related marker E-cadherin was enhanced in bladder cancer." (PMID 38201661, 2024). "The results showed that the MALAT1 expression level in bladder carcinoma cell lines (5637 and T24) was significantly suppressed and the malignant phenotype of bladder cancer cells was alleviated under blue light irradiation." (PMID 36925702, 2023). "By directly interacting with the PRC2 protein SUZ12, MALAT1 functions as a transcriptional regulator in the context of bladder cancer." (PMID 36902032, 2023). "The expression of MALAT1 was shown to be higher in invasive and metastatic bladder cancer compared to normal tissue." (PMID 36685879, 2022). "Clinically, there are many types of lncRNA associated with bladder cancer, including HOTAIR, MALAT1, H19, etc., all of which play an important role in the occurrence and development of bladder cancer." (PMID 33898446, 2021). "The expression level of MALAT1 is the expression in bladder cancer and is related to tumor metastasis and grade." (PMID 34026626, 2021). "For example, MALAT1 regulated cisplatin resistance through the miR-101-3p/VEGF-C axis in bladder cancer and the hindering of MALAT1/miR-199a/ZHX1 axis suppressed the progression of glioblastoma." (PMID 31953613, 2020). "MALAT1 levels in urine and urinary exosomes have been evaluated in prostate and bladder cancer respectively for developing MALAT1 as a non-invasive prognostic biomarker." (PMID 32503170, 2020). "For example, it has been shown that miR-125b can bind to MALAT1 to downregulate its expression and inhibit bladder cancer development." (PMID 32503170, 2020). "In the case of MALAT1 lncRNA, transforming growth factor beta (TGF-β) can promote the epithelial to mesenchymal transition in bladder cancer cells by upregulating MALAT1." (PMID 31733641, 2020). "To date, aberrant expression of MALAT-1 has been found in multiple cancers, such as ovarian, breast, colorectal, and bladder cancers." (PMID 32700729, 2020). "In bladder cancer cells, upregulation of MALAT1 activates the Wnt signaling pathway to promote the endothelial to mesenchymal transition of cancer cells, ultimately enhancing their metastatic capacity." (PMID 31733641, 2020). "In human bladder cancer tissues, MALAT1 gene expression negatively correlates with E-cadherin expression and a high level of MALAT1 significantly correlates with poor patient survival." (PMID 32174966, 2020). "Both in vivo and in vitro studies have shown that MALAT1 can promote migration and metastasis of bladder cancer through inducing EMT." (PMID 30813594, 2019). "The deregulation and function of MALAT1 have been established in several solid tumors, including bladder cancer, lung cancer, colorectal cancer, esophageal squamous cell carcinoma, melanoma, breast cancer, and hepatocellular carcinoma." (PMID 31101802, 2019). "MALAT1 was previously shown to be an important mediator of TGF-β induced EMT signalling in bladder cancer cells." (PMID 31382922, 2019). "They observed that in bladder cancer, hsa-miR-125b and SIRT7 are inversely associated with the oncogenic long non-coding RNA MALAT1." (PMID 30510540, 2018).
bladder cancer (continued). "Up-regulated hsa-miR-125b resulted in down-regulated SIRT7 and MALAT1; this effect inhibited bladder cancer cell growth, induced apoptosis, and decreased cell motility." (PMID 30510540, 2018). "Our result suggested that high expression of MALAT1 was significantly correlated with poor prognosis in OS among patients with bladder cancer." (PMID 29899709, 2018). "Two studies investigated the relationship between the expression of MALAT1 and OS in a total number of 215 bladder cancer patients." (PMID 29899709, 2018). "In fact, the same group had previously identified MALAT1 as a target of miR-125b overexpressed in bladder cancer." (PMID 29570632, 2018). "Reducing MALAT1 expression leads to reduced growth and metastasis in bladder cancer mouse models, making it a potential therapeutic target." (PMID 30281678, 2018). "MALAT1 has been shown to have binding sites for miR-125b, which can downregulate MALAT1 expression and inhibit bladder cancer development." (PMID 28701723, 2017). "MALAT-1 is overexpressed and has been linked to the promotion of EMT in bladder cancer, cervical cancer, NSCLC, pancreatic cancer and renal cell carcinoma." (PMID 28430163, 2017). "The proposed mechanisms of MALAT1 action include the regulation of nuclear-splicing events in a global fashion and through promoting the epithelial-to-mesenchymal transition in bladder cancers." (PMID 28003470, 2016). "A post-transcriptional MALAT1 regulation mechanism mediated by one microRNA (Hsa-miR-125b) has been only reported in bladder cancer." (PMID 27172249, 2016). "Knockout of MALAT1 in bladder cancer animal models resulted in inhibition of malignant cell metastasis by reducing Wnt signaling and thereby suppressing EMT." (PMID 27686732, 2016). "MALAT1 upregulation has been reported in several tumour types and is also a negative prognostic factor in lung, pancreas, colorectal and bladder cancers." (PMID 27172249, 2016). "TGF-β promotes the association of MALAT-1 and SUZ12, thereby promoting bladder cancer cells invasion and metastasis both in vitro and in vivo." (PMID 25428918, 2014). "Certain recent studies have reported that several lncRNAs, including UCA1, MALAT-1 and ncRAN, show marked potential in the field of bladder cancer progression." (PMID 24944692, 2014). "Downregulation of MALAT1 by siRNA, the epithelial-to-mesenchymal transition-related genes, and cell migration of bladder cancer cells are inhibited." (PMID 23843741, 2013). "Screening for novel urinary EV lncRNA candidates for bladder cancer diagnosis identified MALAT1, PCAT-1, and SPRY4-IT1 differential expression to be of high diagnostic value in a training set consisting of 208 urine samples, which was subsequently confirmed in a validation set (160 urine samples)." (PMID 39585046, 2024). "However, in bladder cancer, researchers indicate that MALAT1 interacts with suz12, another PRC2 component, instead of EZH2." (PMID 38674413, 2024). "Moreover, plausible differences in the expression of MALAT-1 between normal and cancerous samples were observed in other cancers, such as bladder carcinoma, thyroid carcinoma, and stomach adenocarcinoma." (PMID 38201661, 2024). "Furthermore, in bladder cancer, the knockdown of MALAT-1 markedly reduced β-catenin accumulation in the nucleus." (PMID 38201661, 2024). "Furthermore, during bladder cancer, MALAT1 was upregulated by TGF-β, which promotes tumor invasion and metastasis, and targeted inhibition of MALAT1 suppressed the migration and invasion properties of TGF-β." (PMID 38674413, 2024). "Moreover, a three exosomal lncRNA panel (RMRP, UCA1 and MALAT1) are elevated in bladder cancer, and is correlated with the tumor stage of bladder cancer." (PMID 37805491, 2023). "MALAT1 in bladder cancer is increased, and its overexpression contributed to cisplatin resistance." (PMID 36793374, 2023). "Additionally, MALAT1 expression was higher in high-grade patients compared to low-grade bladder cancer patients." (PMID 36685879, 2022).
bladder cancer (continued). "Silencing of MALAT1 has an inhibitory effect on the metastatic properties of bladder cancer cells." (PMID 36685879, 2022). "Additionally, MALAT1 has been shown to inhibit apoptotic cell death and thereby promote bladder cancer progression." (PMID 36685879, 2022). "The overexpression of MALAT1 enhances bladder cancer progression and migration." (PMID 36685879, 2022). "FTO promotes bladder cancer tumor growth via MALAT1/miR‐384/MAL2 axis." (PMID 33634966, 2021). "FTO stimulates tumor growth of bladder cancer through regulating MALAT1 methylation." (PMID 33634966, 2021). "Here, MALAT1 expression was related to immune cell infiltrating in lung and bladder cancer." (PMID 34308750, 2021). "Furthermore, the interaction between MALAT1 and miR‐384 was identified in this study, and both of these genes participate in regulating bladder cancer cell viability." (PMID 33634966, 2021). "Additionally, higher urinary exosomal HOTAIR, MALAT1, PCAT-1, higher plasma exosomal H19, and higher serum exosomal UBC1 in NMIBC were associated with poorer prognosis of bladder cancer patients." (PMID 32517366, 2020). "Moreover, they introduced (UCA1-201, UCA1-203, MALAT1, and LINC00355) as a diagnostic panel of lncRNAs in bladder cancer." (PMID 31956395, 2020). "Similarly, it has been reported that there was MALAT1 over expression in a sample of Chinese bladder cancer patients compared with normal margins." (PMID 31956395, 2020). "By association with the other PRC2 component protein SUZ12, MALAT1 decreases E-cadherin expression and increases N-cadherin and fibronectin expression, leading to epithelial mesenchymal transition (EMT), bladder cancer cell migration, and invasion in vitro and tumor metastasis in animal models." (PMID 32174966, 2020). "The silence of MALAT1 could suppress cell motility, proliferation and increased apoptosis in bladder cancer cells." (PMID 30988072, 2019). "MALAT1 plays a critical role in the metastasis phenotype of lung, gastric, and bladder cancers." (PMID 32099603, 2019). "Moreover, in bladder cancer, overexpressed MALAT1 promotes TGFβ-driven bladder cancer metastasis by directly interacting with PRC2 subunit Suz12 to repress E-cadherin expression." (PMID 29685978, 2018). "The finding that metastasis-associated lung adenocarcinoma transcript 1 (MALAT1) behaves as a ceRNA targeting tumor suppressor miR-125b unveiled a negative feedback loop in bladder cancer." (PMID 29570632, 2018). "Serum MALAT1 was also found upregulated in bladder cancer patients compared to healthy individuals and could likely a represent a novel independent biomarker for the diagnosis or recurrence of this cancer." (PMID 29739426, 2018). "Moreover, Ying and colleagues showed that MALAT1 promoted bladder cancer cell migration and metastasis by inducing EMT." (PMID 29739426, 2018). "Similarly, other overexpressed lncRNAs namely TUG1 and MALAT1 were also found to act as ceRNA in bladder cancer and cervical cancer." (PMID 29719612, 2018). "In contrast, another study indicated that miRNA-125b may suppressed lncRNA MALAT1 expression level in bladder cancer." (PMID 28187000, 2017). "In bladder cancer, MALAT1 is inversely expressed with miR-125b." (PMID 29147648, 2017). "Furthermore, MALAT1 silencing was also shown to result in decreased bladder cancer cell growth, motility, and increased apoptosis." (PMID 26978351, 2016). "Interestingly, the Wnt signaling pathway is activated when MALAT1 overexpression promoted epithelial-mesenchymal transition (EMT) in bladder cancer." (PMID 24006935, 2013). "Therefore, MALAT1 knockdown can be a potential therapy for bladder cancer." (PMID 36163080, 2022). "Similarly, in bladder cancer cells, MALAT1 gene expression is activated by TGFβ." (PMID 32174966, 2020). "Furthermore, SPRY4-IT1, MALAT1, linc-UBC1, lncRNA-LET, ZEB2-AS1, XIST, PVT1, and SNHG16 were significantly associated with lymph node metastasis status in patients with bladder cancer." (PMID 29899709, 2018).